AGO2 (argonaute RISC catalytic component 2)
Diseases named in the same sentence as AGO2 in open-access papers (continued):
Sharing a sentence is not in itself a finding about the gene and the disease.
breast carcinoma (continued). "Although we recently demonstrated that miR-34a directly targets tRNAiMet precursors via Argonaute 2 (AGO2)-mediated cleavage, consequently attenuating the proliferation of breast cancer cells, whether tRNAiMet fragments derived from this cleavage influence breast tumor angiogenesis remains unknown." (PMID 35961977, 2022). "This suggests that Let-7a targets will be strong downstream targets of the LASP1-Ago2 interaction as they are upregulated in advanced breast cancer, and miR-100 targets outside of Ago2 itself may not be strong targets." (PMID 32872485, 2020). "Furthermore, we did not observed any correlation between the levels of Ago2 expression and survival in any of the breast cancer subtypes." (PMID 31506588, 2019). "In summary, our findings show that Ago2 downregulation could be an effective strategy to upregulate STIM1 expression as observed in MDA-MB-231 cells, suggesting it as one potential mechanism to control STIM1 expression during breast cancer development." (PMID 31506588, 2019). "Importantly, no significant Ago2 gene deletion was observed in this breast cancer cohort (4/3562 samples, 0.11%)." (PMID 31324173, 2019). "Combined with Ago2 mRNA expression data demonstrating a correlation with DFS overall, we believe that measuring both Ago2 mRNA and protein levels may hold further promise in aiding the stratification of breast cancer." (PMID 31324173, 2019). "There are four argounatue (AGO) proteins in humans AGO1–4 and evaluation of alterations in AGO1–4 gene expression across breast cancer cell lines and tumor samples has shown that AGO2 is increased in ER− samples versus ER+ while there is no change in AGO1, AGO3, or AGO4." (PMID 26062653, 2015). "To identify which miRNA-target pairs are more likely to display regulation, we used AGO2-PAR-CLIP to capture biochemical miRNA targets and define their specific location within 3′ UTRs and CDSs, in the MCF7 luminal subtype and ER-positive/HER2-negative breast cancer ductal cell line." (PMID 24398324, 2014). "While Ago2 plays an essential role in the regulation of molecules and pathways with known involvements in the initiation and progression of breast cancer, Ago2 levels in breast cancer have not been investigated or correlated with key clinicopathological criteria (such as survival)." (PMID 31324173, 2019).
colon cancer (27 papers, 2010 to 2025). "AGO2 was found to localize to multivesicular endosomes (MVEs) during exosome biogenesis, but when AGO2 is phosphorylated by the activation of KRAS–MEK signaling in colon cancer cells the AGO2–endosome association and sorting to exosomes is inhibited." (PMID 33233600, 2020). "Overexpression of AGO2 in colon cancer was positively associated with distant metastases." (PMID 28903378, 2017). "Previously, a number of studies have demonstrated deregulation of miRNA in gastric cancer and the importance of the entire microRNA system has been documented in both gastric and colon cancer by the presence of cancer-specific mutations in the key RISC components AGO2 and TNRC6A." (PMID 21418558, 2011). "The observed nuclear localization of AGO2 in 3D tumor spheroid culture, in combination with our observation of changes in the expression of miRISC target genes associated with cell migration, encouraged us to next examine AGO2 localization in human colon tumor tissue." (PMID 38109320, 2024). "Notably, the TCGA data analysis also showed that DROSHA and Ago2 levels are significantly elevated in colon tumors, in addition to the loss of their junctional localization, revealing multiple levels of dysregulation of these proteins correlating with tumor progression." (PMID 32272708, 2020). "This newly formed Ago2/Trp/miR‐193a‐3p complex is more efficient than miR‐193a‐3p alone in inhibiting the expression of targeted genes and inhibiting colon cancer liver metastasis." (PMID 39031551, 2024). "Our laboratory has previously used CRISPR/Cas9-mediated knockout cells deficient for the primary AGO variants AGO1, AGO2 and AGO3 to examine the scope of RISC-mediated regulation in the cytoplasm and nuclei of HCT116 colon cancer-derived cells." (PMID 38109320, 2024). "Recent studies have revealed that Ago1 and Ago2 play an important oncogenic role in breast and colon cancer." (PMID 28977858, 2017). "The studies reveal that tryptophan/miR/Ago2 complex inhibits mouse colon cancer liver metastasis." (PMID 39031551, 2024). "Proposed model of amino acid modulates the miR activity by directly binding to miR, subsequently enhancing Ago2 RNase activity via binding to Trp bound pockets of Ago2 for increasing miR mediated inhibition of expression of targeted genes, leading to inhibition of colon cancer liver metastasis." (PMID 39031551, 2024). "As described in colon cancer, monitoring of Ago2 as well as Ago2-miRNA levels in the blood of gastric cancer patients may be a possible marker of tumor progression and response to chemotherapy." (PMID 34068319, 2021). "It has recently been shown that mutant KRAS in colon cancer cell lines leads to decreased Ago2 secretion in exosomes and Ago2 knockdown resulted in decreased secretion of let-7a and miR-100 in exosomes whilst cellular levels of the respective miRs remained unchanged compared to control cells." (PMID 27358717, 2016). "We show nuclear enrichment of AGO2 in HCT116 cells grown in two-dimensional culture to high density, HCT116 cells grown in three-dimensional tumor spheroid culture, and human colon tumors." (PMID 38109320, 2024). "In colon cancer, during exosome biogenesis, AGO2 localizes to multivesicular endosomes, but phosphorylation by KRAS–MEK signaling dissociates AGO2 from endosomes and sorting to exosomes is inhibited." (PMID 35562884, 2022). "Pancreatic ductal adenocarcinoma and colon cancer patients with high levels of TP63 and Ago2 had a significantly lower overall survival time." (PMID 35459267, 2022).
colon cancer (continued). "Since Ago2 is recruited into the Trp/miR complex in the CT26 cells, we further tested whether Ago2 is colocalized with Trp in human colon tumor tissue and mouse metastatic liver tissue." (PMID 39031551, 2024). "Western blot analysis for the presence of Ago2 in the Trp complex indicated that Ago2 can be detected by streptavidin pulldown of biotin labeled Trp complex isolated from the human colon cancer cell line SW620, suggesting that Ago2 is present in the Trp complex isolated from tumor cells." (PMID 39031551, 2024).
gastric cancer (27 papers, 2011 to 2025). A primary or metastatic malignant neoplasm involving the stomach. "Wilms tumors often carry a deletion of three AGO genes, and mutations of AGO2 were frequently found in colorectal and gastric cancers." (PMID 24763381, 2014). "tRF-33-P4R8YP9LON4VDP inhibits gastric cancer by regulating STAT3 signaling in an AGO2-dependent manner." (PMID 40565315, 2025). "Conversely, tRF-33-P4R8YP9LON4VDP inhibits gastric cancer by regulating STAT3 signaling in an AGO2-dependent manner." (PMID 40565315, 2025). "The oncogenic circAGO2 (hsa_circ_0135889) derived from AGO2 gene intron 1 bound to HuR and promoted its export to cytoplasm and binding to mRNA 3′UTR, thus suppressing AGO2-miR interaction and mRNA degradation of multiple oncogenes in gastric cancer cells." (PMID 37993879, 2023). "Authors of this study showed that, by impeding the binding of YY1 to the MMP-14 promoter, an AGO2–miR-584-3p complex can suppress the tumorigenesis and aggressiveness of gastric cancer cells, both in cell lines and xenograft tumors." (PMID 35327968, 2022). "AGO2 upregulation has been discovered in several tumor types, including breast, colon adenocarcinoma, hepatocellular carcinoma, and gastric carcinoma." (PMID 36185235, 2022). "Despite the described upregulation of AGO2 in gastric cancer, decreased expression of AGO2 was found in HER-2-positive cases, adding complexity to the potential application of AGO2 for grading gastric cancer patients." (PMID 33668654, 2021). "The target mRNAs in the Argonaute2 (Ago2) complex of nucleus and cytoplasm of gastric cancer cells were analyzed through Gene ontology (GO) and Kyoto encyclopedia of genes and genomes (KEGG) analysis." (PMID 30621629, 2019). "In this study, the miRNAs and their target mRNAs in the Argonaute2 (Ago2) complex of nucleus and cytoplasm of gastric cancer cells were characterized using high-throughput sequencing of RNAs isolated by crosslinking immunoprecipitation (HITS-CLIP)." (PMID 30621629, 2019). "Consistent with previous studies, our study characterized 243 miRNAs and 265 miRNAs in the Ago2 complexes of nucleus and cytoplasm of gastric cancer cells in this study." (PMID 30621629, 2019). "Knockdown of AGO2 attenuated the transcriptional repression of MMP-14 induced by ectopic expression of miR-584-3p in gastric cancer cells." (PMID 28827574, 2017). "We found that AGO2 was enriched surrounding the binding site of miR-584-3p within MMP-14 promoter in gastric cancer cells." (PMID 28827574, 2017). "Collectively, these data suggested that miR-584-3p interacted with AGO2 to repress the YY1-facilitated MMP-14 transcription in gastric cancer cells." (PMID 28827574, 2017). "Stable over-expression of miR-584-3p resulted in increased binding of AGO2 and epigenetic markers EZH2, EHMT2, H3K27me3 and H3K9me2, and decreased binding of YY1 to MMP-14 promoter in gastric cancer cells, which was attenuated by knockdown of AGO2." (PMID 28827574, 2017). "Since AGO2 is essential for miRNA-directed implementation of silent-state chromatin modification at gene promoters, we further observed the functions of AGO2 in miR-337-3p-repressed MMP-14 expression in gastric cancer." (PMID 27259238, 2016). "Western blot, real-time quantitative RT-PCR, and dual-luciferase assays demonstrated that knockdown of AGO2 abolished the miR-337-3p-induced transcriptional repression of MMP-14 in gastric cancer cells." (PMID 27259238, 2016). "We found that AGO2 was enriched surrounding the binding site of miR-337-3p within MMP-14 promoter in gastric cancer cells." (PMID 27259238, 2016). "Collectively, these results indicated that miR-337-3p recognized the binding site and recruited AGO2 to repress the MMP-14 transcription in gastric cancer cells." (PMID 27259238, 2016).
gastric cancer (continued). "In addition, RNA-binding protein immunoprecipitation(RIP) assay of gastric cancer cell extracts revealed that TRPM2-AS binds directly to Ago2 which is the key component of the RNA-induced silencing complex mediated by miRNA." (PMID 32123162, 2020). "The results of Ago2 RIP assays proved that cir-ITCH could bind to a number of miRNAs in gastric cancer, but which miRNAs were bound by cir-ITCH remained unknown." (PMID 33060778, 2020). "For instance, AGO2 expression levels in primary gastric cancer and corresponding lymph node metastases are significantly higher than that in healthy controls, whereas AGO2 expression is lower, corresponding reduced RNAi efficiency, in melanoma compared with primary melanocytes." (PMID 29263891, 2016). "In addition, HOTAIR:miR-331-3P coimmunoprecipitation with anti-Ago2 demonstrated a physical interaction in gastric cancer cells, providing further support for HOTAIR’s miRNA-sequestering activity." (PMID 24775712, 2014). "We then performed similar BGLF2-FLAG IPs (with RNase A treatment) in AGS gastric carcinoma cells, commonly used to study EBV lytic infection, and again confirmed recovery of Ago2 and TNRC6A." (PMID 35007297, 2022). "In gastric cancer, miR-337-3p inhibit myeloid zinc finger 1 (MZF1) induced transcriptional activation of MMP-14 through recruiting Ago2 and inducing repressive chromatin remodeling." (PMID 29471827, 2018). "Indeed, in gastric cancer cells, the authors found that miR-584-3p binds to the MMP-14 promoter in an AGO2-dependent manner, leading to increased levels of the repressive histone marks H3K27me3 and H3K9me2." (PMID 35327968, 2022). "As we expected, the RIP assay showed that GAGE7B-3’UTR was enriched in AGO2 pellets relative to the negative control; p38δ-3’UTR-1 was also enriched in AGO2 pellets relative to negative controls in gastric cancer, though not as much as GAGE7B-3’UTR was." (PMID 30871606, 2019). "In addition, treatment of gastric cancer cells with RNase H, but not with RNase A, abolished the enrichment of AGO2 on the MMP-14 promoter in." (PMID 28827574, 2017). "In addition, RNase H treatment, but not RNase A treatment, abolished the enrichment of AGO2 on the MMP-14 promoter in gastric cancer cells." (PMID 27259238, 2016). "A Korean study of 2010 evaluated AGO1, AGO2, TNRC6A, TNRC6C, TARBP2 and XPO5 mutations in colorectal (CRC) and gastric cancers (GC), with or without microsatellite instability." (PMID 23586049, 2013). "Knockdown of AGO1, but not of Argonaute 2 (AGO2), Argonaute 3 (AGO3) or Argonaute 4 (AGO4), abolished the miR-558-facilitated protein and transcriptional levels of HPSE in gastric cancer cells." (PMID 27685626, 2016).
glioma (27 papers, 2016 to 2023). A benign or malignant brain and spinal cord tumor that arises from glial cells (astrocytes, oligodendrocytes, ependymal cells). "IRF7 was shown to promote glioma cell invasion as well as chemoresistance and radiation resistance by inhibiting the expression of argonaute 2 (AGO2), a regulator of microRNA maturation, biosynthesis, and function." (PMID 37251373, 2023). "The elevation of AGO2 levels was observed in glioma and breast cancer cells, suggesting the involvement of RNA silencing effects of miRNA upon pristimerin treatment." (PMID 34026649, 2021). "The assessment of AGO2 mRNA and protein levels in 129 glioma specimens uncovered the correlation between elevated expression of AGO2 and lower overall survival, as well as progression-free survival." (PMID 33668654, 2021). "In conclusion, pristimerin inhibited glioma progression through AGO2 and PTPN1 expression via a canonical miRNA-mediated mechanism." (PMID 31015365, 2019). "RIP assay results show that circPRKCI and miR-545 were both efficiently pulled down by anti-Ago2 antibody in A172 glioma cells." (PMID 31409777, 2019). "Subsequently, the effects of miR-542-5p on RISC and proliferation associated gene AGO2 and PTPN1 were evaluated in glioma cells." (PMID 31015365, 2019). "In summary, the present study revealed that pristimerin participated in the proliferation, apoptosis of glioma cells and demonstrated that AGO2 and PTPN1 were partially responsible for the miR-542-5p induced inhibition of cell proliferation." (PMID 31015365, 2019). "It is reported that AGO2 can regulate tumor invasion, proliferation, apoptosis and cell cycle in glioma, cervical and prostate cancer." (PMID 27764782, 2016). "It manifested that miR-384-agomiR could effectively inhibit the fluorescence activity of LINC01087-WT, while RIP analysis found that both LINC01087 and miR-384 were enriched by anti-Ago2 in glioma cell lysate." (PMID 34459789, 2021). "Inhibited Glioma progression by targeting AGO2 and PTPN1 expression via miR-542-5p." (PMID 34026649, 2021). "Twenty-two vital RBPs, IGF2BP1, IGF2BP3, EIF4A3, hnRNPC, and AGO2, can bind to circRNAs and may play important biological functions in glioma." (PMID 33323543, 2020). "Recently, AGO2 has been demonstrated as a potential oncogene in human tumorigenesis, including head and neck squamous cell carcinoma, nasopharyngeal carcinoma, bladder cancer, and glioma." (PMID 32420319, 2020). "This supports previous work that reported that high Ago2 protein expression in Glioma and correlates with poorer survival, suggesting potentially that further work may establish a common role for Ago2 in cancer progression." (PMID 31324173, 2019). "The glioma cells were transfection of miR-542-5p inhibitor and control for 48 h, and treated with or without pristimerin (1 μM) for 24 h, then qRT-PCR was performed to determine the expression of AGO2 and PTPN1." (PMID 31015365, 2019). "Furthermore, miR-542-5p silence with siRNA in glioma cells lead to the elevation in AGO2, and decreased PTPN1 level." (PMID 31015365, 2019). "Furthermore, we proved that in low concentration, pristimerin inhibited the viability of glioma cells through AGO2, and suppressed expression PTPN1 via a canonical miRNA-mediated silencing mechanism, while in high concentration, pristimerin induced apoptosis." (PMID 31015365, 2019). "We showed that a significant proportion of MSI1 was cytosolic in samples from patients with high grade glioma but it remains unclear whether MSI1/AGO2 pathway actively participates to tumorigenicity in patients and could also have an impact on tumor recurrence." (PMID 31903115, 2020). "Defuse glioma patients with PTPN1, and AGO2 mutation showed worse overall survival both in the overall group (p = 3.86 × 10−8) and disease-free/progression-free group (P=2.85 × 10−5), indicating that PTPN1 and AGO2 may play important roles in diffuse glioma and were related to survival rate." (PMID 31015365, 2019).